HIF1A (hypoxia inducible factor 1 subunit alpha)
Diseases named in the same sentence as HIF1A in open-access papers (continued):
Sharing a sentence is not in itself a finding about the gene and the disease.
bacterial infection (continued). "Since we have previously shown a general activation of hypoxia inducible factor (HIF-1α) in bacterial infections, we hypothesized that HIF-1α, via induction of vascular endothelial growth factor (VEGF) is involved in transmigration of pathogens across the BBB." (PMID 32529267, 2020). "We therefore speculated that upregulated inflammatory factors and low-grade bacterial infection participate in the activation of the Notch and HIF-1α pathways and subsequent initiation of IVD degeneration in patients with MCs, particularly MC I and MC II." (PMID 32723315, 2020). "Since HIF-1α is also involved in host immune response to bacterial infection, we initially also asked whether NleB affected the host immune response by modifying HIF-1α." (PMID 30125331, 2018). "Up-regulated expression of the HIF-1α transcript has been observed during bacterial infection." (PMID 28542591, 2017). "Hypoxia signalling is upregulated in cell-line and in murine macrophage models of bacterial infection, and HIF-1α overexpression is known to upregulate the antimicrobial activities of leukocytes, including phagocytosis, bacterial killing and leukocyte lifespan." (PMID 26512123, 2015). "Several studies had provided evidence for HIF1A stabilization during bacterial infections." (PMID 24086109, 2013). "In response to LPS and bacterial infections NFκB binding to HIF-1α promoter is further increased." (PMID 22701652, 2012). "Therefore, we next sought to determine whether the surge in HK2-mediated glycolysis in human gingival fibroblasts after bacterial infection was a result of HIF-1α activation." (PMID 36793034, 2023). "Conversely, mice lacking HIF-1α are more susceptible to bacterial infection." (PMID 36761171, 2022). "However, as VEGF is known to induce paracellular permeability in brain ECs and given the paracellular localization of S. pneumoniae in these cells, we investigated whether the permeability upon bacterial infection is mediated by HIF-1α/VEGF pathway." (PMID 32529267, 2020). "It is noteworthy that HIF-1α may also exert regulatory effects in normoxia, in particular during bacterial infection, where HIF-1α expression is stimulated through TLR receptor engagement and cell signaling pathways (such as NF-κB and MAPK) [for review see Ref." (PMID 25505468, 2014). "Apart from HIF-1α, NRF2 also plays a central role in regulating Mφ inflammatory responses against bacterial infections, particularly its role in regulating the transcription of its targeted genes." (PMID 39119289, 2024). "Therefore, metabolic reprogramming, causing a change from oxidative phosphorylation to glycolysis, can promote HIF-1α signaling pathway activation, which can further enhance glycolysis, in a vicious cycle that promotes proinflammatory responses in human gingival fibroblasts upon bacterial infection." (PMID 36793034, 2023). "The increased expression of HIF1α in C. rodentium-challenged protegrin-treated groups compared to C. rodentium-challenged PBS-treated mice further suggests PG-1 may play a role in enhancing host protection from bacterial infection, which is also reflected at the physiological level." (PMID 34502403, 2021). "Accordingly, induction of the HIF-1-regulated VEGF was detected in bacterial infections with S. aureus, P. aeruginosa and E. coli by VEGF mRNA induction whereas HIF-1α mRNA transcript levels itself again appeared unaffected." (PMID 20644645, 2010). "Hypoxia and HIF-1α increase expression of integrins ITGA5, ITGβ1, which could potentially create a positive feedback for enhancing further bacterial infection." (PMID 38535967, 2024). "Similar to HIF-1α, NRF2 also plays an essential role in mediating Mφ responses against bacterial infection, primarily by enhancing its phagocytic abilities through upregulating its targeted scavenger reports, as well as maintaining a favorable redox environment and cell survival." (PMID 39119289, 2024).
bacterial infection (continued). "To explore the involvement of the HIF-1α–VEGF signaling pathway in mammalian respiratory barrier dysfunction during respiratory bacterial infection, we examined the expression levels of VEGFA and HIF-1α in MLE-12 cells after bacterial infection for 6 h." (PMID 36916939, 2023). "Hypoxia-inducible factor 1-alpha (HIF-1α), the primary regulator of cell response to hypoxia, has been reported to be widely involved in the mechanism of hypoxic metabolism and has become an essential regulator of bacterial infection." (PMID 34898382, 2022). "During skin injury under sterile conditions, the absence of HIF-1α in NK cells accelerates skin repair, yet, at the expense of a compromised antimicrobial defence upon bacterial infection." (PMID 34349124, 2021). "In addition, the role of HIF-1α as a metabolic regulator in the immune function of macrophages is confirmed by the fact that HIF-1α-mediated glycolysis was reported to be essential for the function of pro-inflammatory macrophages to protect against fungal and bacterial infections." (PMID 36614031, 2022). "In accordance with our data showing the contribution of HIF-1α in the control of bacterial infection, it was likewise demonstrated that macrophage killing of the Gram-positive pathogen group A Streptococcus and the Gram-negative bacterium Pseudomonas aeruginosa was impaired upon HIF-1α deletion." (PMID 33989349, 2021).
cardiovascular diseases (48 papers, 2014 to 2025). "Recent research has identified that genetic variations in HIF1A are associated with over 40 different phenotypes and diseases, such as cancer, cardiovascular diseases, and metabolic disorders." (PMID 37239335, 2023). "Previous review showed that a number of hypoxia-mediated miRNAs that have been implicated in pathogenesis of cardiovascular diseases modulated by hypoxia or HIF1α." (PMID 35091561, 2022). "Taken together, our results are compelling evidence of the role of HIF-1α-controlled pathways in increasing the risk of cardiovascular diseases in the offspring of diabetic mothers." (PMID 29753320, 2018). "HIF-1α activation not only influences the proliferation and migration of VSMCs but also induces their transformation into osteoblast-like cells, promoting calcification, which is closely linked to the development and progression of cardiovascular diseases." (PMID 39766299, 2024). "Animal experiments showed that the elimination of Hif-1α gene, which encoded Hif-1α protein synthesis, stopped the progression of fetal development during days 8 to 9 and led to lethal fetal conditions during days 10 to 11, along with cardiovascular disorders and decreased hematopoiesis." (PMID 37878989, 2023). "Together our findings provide evidence that a global reduction in Hif1a gene dosage increases predisposition of the offspring exposed to maternal diabetes to cardiac dysfunction, and also underscore Hif1a as a critical factor in the fetal programming of adult cardiovascular disease." (PMID 29753320, 2018). "As an important regulatory factor in cardiovascular diseases, we also analyzed the expression of HIF-1α signaling pathway, and found HIF1A was downregulated in CAD samples." (PMID 40950552, 2025). "In cardiovascular diseases, HIF1A is involved in the adaptation of the heart and blood vessels to low oxygen levels." (PMID 39453113, 2024). "Accumulating studies have shown that HIF1A plays a crucial role in the inflammation process of cardiovascular disease (CVD) including AD." (PMID 39479394, 2024). "Despite the considerable attention HIF‐1α has attracted as a target for revascularization in peripheral ischemic tissues, there is a limited knowledge on the effects of HIF‐1α‐based therapies in atherosclerotic cardiovascular diseases in aging." (PMID 37957823, 2023). "Existing connections between CRL2 and cardiovascular disease are mostly attributed to HIF1α (hypoxia-inducible factor 1α), a well-studied oxygen-responsive substrate of CRL2." (PMID 35327608, 2022). "Modulating HIF‐1α activity or expression may become a new therapeutic strategy for various disorders, including tumors, cardiovascular diseases, and neurodegenerative diseases." (PMID 40944417, 2025). "Continuing studies show that HIF-1α and mRNAs play important roles in cardiovascular disease (CVD)." (PMID 37005512, 2023). "Furthermore, the cardinal significance of HIF-1α extends beyond cardiac regeneration, encompassing its active involvement in cardiovascular diseases." (PMID 37981648, 2023). "HIF1α is closely related to cardiovascular diseases in multiple dimensions." (PMID 35327608, 2022). "VEGF-A is one of the most important HIF-1α-dependent target genes in cardiovascular disease." (PMID 36497143, 2022). "HIF-1A is expressed in various cells of the cardiovascular system to varying degrees, which significantly affects cell function and plays an important role in many cardiovascular diseases." (PMID 35069552, 2021). "The aim of this article is to comprehensively review the role of HMGB1, HIF-1α, and VEGF in DOX-induced Cardiovascular Disease and its molecular mechanisms." (PMID 35340325, 2022). "In the prevention and treatment of cardiovascular diseases, berberine mainly protects cardiac function by activating the PINK1-Parkin, HIF-1α/BNIP3 signaling pathways and promoting mitophagy." (PMID 36034426, 2022).
cardiovascular diseases (continued). "HMGB1, HIF-1α and VEGF has a pivotal regulator in DOX-induce cardiomyocyte damage in cardiovascular diseases which predominantly acts through different pathways." (PMID 35340325, 2022). "•HMGB1, HIF-1α, and VEGF in cardiovascular diseases will be predominantly acting through different pathways." (PMID 35340325, 2022). "We identified several important pathways for cardiovascular disease, such as insulin, IGF1 and glucose signaling pathways, TGF-β pathway, as well as hypoxic and oxygen homeostasis regulation of HIF-1-α (and for a complete list)." (PMID 27317124, 2016). "One of the main challenges is to clarify their interaction with hypoxia-inducible factor 1 alpha (HIF-1α), the lack of which leads to oncological and cardiovascular diseases." (PMID 36674808, 2023). "Based on the background and previous findings, a study to more completely will be urgent to understand in the effect of induction of Doxorubicin (DOX) on changes in HMBG1, HIF-1α and VEGF which may be a mechanism for cardiovascular disorders." (PMID 35340325, 2022). "Several articles were revealed that molecular mechanisms of the DOX in cardiomyocyte damage and related to HMGB1, HIF-1α and VEGF and may potential treatment and prevention to cardiovascular disease in DOX intervention." (PMID 35340325, 2022).
adenocarcinoma (44 papers, 2005 to 2025). A common cancer characterized by the presence of malignant glandular cells. "Consistent with findings in MLE12 cells, we observed that the ablation of a single RNF20 allele in the human A549 adenocarcinoma cell line led to increased levels of HIF1α and γH2AX." (PMID 40436847, 2025). "As a result, HIF-1α expression was found in the cytoplasm of adenocarcinoma and stroma in the low group." (PMID 35780404, 2022). "Tissue microarrays of human OvCa showed elevated expression of CX3CR1 and HIF-1α compared to normal cells, and their levels were higher in adenocarcinoma stages II and III." (PMID 31077234, 2019). "The expressions of CX3CR1 and HIF-1α were particularly high in adenocarcinomas of stages II and III, compared to normal OvCa tissues." (PMID 31077234, 2019). "In that respect, an earlier study was able to show that the induction of the Nrf2 pathway in NOX1-expressing adenocarcinoma A549 cells augments HIF-1α signaling." (PMID 27286880, 2016). "Expression of HIF-1α protein was demonstrated both in mammary adenomas and adenocarcinomas in bitches." (PMID 24153191, 2013). "Mann–Whitney test revealed significant differences in HIF-1α expression between particular malignancy grades of adenocarcinomas (G1 vs. G2 - P < 0.0001; G1 vs. G3 - P < 0.0001; G2 vs. G3 – P = 0.02)." (PMID 24153191, 2013). "G3 adenocarcinomas exhibited HIF-1α expression at + level in over 14% of cases, at ++ level in over 28% of cases and at +++ level in over 57% of cases." (PMID 24153191, 2013). "In accordance with results presented here, a decrease of HIF-1α after BA treatment has been described in adenocarcinoma cells." (PMID 21906280, 2011). "Two cases of adenocarcinomas were previously shown to contain cells with cytoplasmic HIF1α and NE marker, chromogranin." (PMID 20663134, 2010). "The frequent diffuse type of HIF-1α overexpression is in contrast with most adenocarcinomas where usually perinecrotic, hypoxia induced HIF-1α expression is seen." (PMID 16035955, 2005). "However, COPD- and adenocarcinoma-like phenotypes were observed in their offspring when CC-LR mice were bred with transgenic animals overexpressing human HIF-1α in airway epithelial cells." (PMID 36338690, 2022). "We compared noncancerous and lung‐adenocarcinoma human samples for hypoxia‐inducible factor 1‐alpha (HIF‐1A), microRNA‐210‐3p (mir‐210‐3p), and CCL2 levels." (PMID 35658112, 2024). "Interestingly, when BIRC5/HIF1A/FLT4 were upregulated in LUAD tissues, they exhibited a high presence in solid pattern-predominant adenocarcinomas, which are large and aggressive tumors with poor prognoses." (PMID 37509650, 2023). "In addition, when CC-LR mice were bred with transgenic animals that overexpress a constitutively active mutant form of human HIF-1α in the airway epithelium, both COPD- and adenocarcinoma-like phenotypes were observed." (PMID 30250643, 2018). "Interestingly in the spontaneous autochthonous transgenic adenocarcinoma of mouse prostate (TRAMP) model, Prx1 expression is increased at the time of transformation, while HIF-1α and VEGF expression is elevated in PIN lesions." (PMID 23185615, 2012). "HIF-1α expression decreased from NSE to CLO and then increased with progression to adenocarcinoma." (PMID 17437013, 2007). "Although HIF-1α is of interest as a marker of hypoxia, its increase in expression from CLO to adenocarcinoma might be inflammatory mediated." (PMID 17437013, 2007). "Moreover, whereas about 75% of glands contained PINs or adenocarcinoma in sham‐operated Pten/Hif1a(i)pe−/− mice, > 80% of glands in castrated ones had a neoplastic‐free appearance and no adenocarcinoma was observed." (PMID 37070472, 2023).
adenocarcinoma (continued). "In experiments using adenocarcinoma A549 cells, intermittent hypoxic culture increased protein expression, but gene expression was not affected by HIF-1α and some related genes, suggesting that various oxygenation conditions may directly affect these factors at the protein level." (PMID 40168275, 2025).
kidney disease (39 papers, 2012 to 2026). "Currently, research efforts aimed at inhibiting HIF-1α activity and its related pathways are predominantly concentrated in the oncology domain, with a notable deficiency in studies pertaining to renal diseases, particularly DKD." (PMID 39995420, 2025). "We identified six common target genes associated with renal diseases, and three (HIF1A, FOXO1, KLF4) are related specifically with LN." (PMID 32085620, 2020). "However, beneficial effect of Sirt1 activation has not been reported in association with its deacetylation targeting HIF‐1α in the kidney disease." (PMID 30614190, 2019). "Our findings suggest that ZnO NP-induced autophagy is associated with HIF-1α signaling, which may be an important mechanism and protective outcome of kidney diseases caused by ZnO NPs." (PMID 27678081, 2016). "Current research on HIF-1α in the context of renal diseases predominantly addresses the management of renal anemia, a topic that has been extensively reviewed in prior literature." (PMID 39995420, 2025). "In the present study, the functions of HIF-1α CTAD in hypoxia-induced kidney diseases were investigated employing the HIF-1α CTAD−/− mice." (PMID 37225700, 2023). "Here, we established the HIF-1α CTAD knockout (HIF-1α CTAD−/−) mice to assess the potential pathophysiological function of HIF-1α CTAD in hypoxic kidney disease." (PMID 37225700, 2023). "A previous study showed that HIF-1α, Snail, and other upstream signal molecules induced by injury regulate Twist1 transcriptional activation in renal disease." (PMID 35182235, 2022). "We chose HIF-1α as a molecular marker for detection of oxygen levels because it is popular in studies on kidney disease, which is a closely related to hypoxia and renal anemia." (PMID 34267672, 2021). "HIF-1α is a key transcription factor, and it can promote the pathogenesis of renal diseases such as DN through upregulation of RAGE and NF-κB activation." (PMID 33049944, 2020). "The investigation of HIF‐1α is particularly valuable in kidney disease since HIF‐1α is expressed predominantly in tubular cells, and tubules are susceptible to hypoxia." (PMID 32975326, 2020). "Some studies on renal diseases found that HIF-1α played a protective role, but others reported that it was a risk factor." (PMID 32884936, 2020). "Although HIF-1, a master transcription factor for cellular adaptations to hypoxia, plays a critical role in protection against hypoxia-induced kidney diseases, the precise effects of HIF-1α CTAD on hypoxic kidney diseases remain unclear." (PMID 37225700, 2023). "In this study, we first demonstrated that HIF-1α CTAD could exert a protective role against hypoxia-induced kidney diseases through transcriptional regulation of HK2." (PMID 37225700, 2023). "In terms of therapeutic applications, inhibition of MAGED2 could target the oncoproteins Gαs and HIF-1α specifically in hypoxic tumors, and its activation may enhance HIF-1α induction in kidney disease." (PMID 36359819, 2022). "Given the well-established link between HIF-1α and cAMP/PKA and by showing in the present study that MAGED2 is also required for hypoxic induction of HIF-1α, the finding of the present study may further explain the transient nature of this kidney disease." (PMID 36359819, 2022). "This review summarizes the mechanisms of HIF-1α regulation in renal disease." (PMID 36364144, 2022). "A study also proved that GLUT1 was the downstream gene of HIF-1α in T2DM renal disease." (PMID 35833024, 2022). "Evidence shows that Nox4 interplays with HIF1α and plays a critical role in various renal diseases." (PMID 35966094, 2022). "The molecular mechanism of kidney disease is extremely complex, and many factors, such as NCOAs, HIF-1α, and VEGF, may be involved in its pathogenesis and progression." (PMID 32884936, 2020). "More studies should be conducted to assess the detailed role of HIF-1α in renal disease." (PMID 32884936, 2020).